TXNIP (thioredoxin interacting protein)
Diseases named in the same sentence as TXNIP in open-access papers (continued):
Sharing a sentence is not in itself a finding about the gene and the disease.
lung adenocarcinoma (13 papers, 2020 to 2025). A carcinoma that arises from the lung and is characterized by the presence of malignant glandular epithelial cells. "NCL overexpression suppresses CD8+ T cell glucose metabolism and anti-tumor immune function, promoting lung adenocarcinoma progression via the MYC/TXNIP axis." (PMID 40346484, 2025). "For instance, circDCUN1D4 can bind to the HuR protein and acts as a scaffold to facilitate the interaction of HuR and TXNIP mRNA, thereby increasing the stability of TXNIP mRNA to delay lung adenocarcinoma progression." (PMID 37723588, 2023). "For example, circDCUN1D4 can strengthen the interaction between HuR protein and TXNIP mRNA to maintain the stability of TXNIP mRNA, which are involved in the metastasis and glycolysis of lung adenocarcinoma (LUAD)." (PMID 36139074, 2022). "This complex enhanced the stability of the TXNIP mRNA and suppressed metastasis and glycolysis of lung adenocarcinoma." (PMID 35986300, 2022). "Furthermore, circDCUN1D4 interacts with HuR and inhibits glycolysis and metastasis in lung adenocarcinoma via stabilizing TXNIP mRNA." (PMID 40612865, 2025). "One study showed that sodium butyrate affects proliferation and migration of A549 cells by activating the TNF receptor-associated factor 6 (TRAF6)-thioredoxin-interacting protein (TXNIP) pathway, suggesting that sodium butyrate has an effective therapeutic effect on lung adenocarcinoma." (PMID 37180438, 2023). "Furthermore, in lung adenocarcinoma, circdcun1d4 can bind the HuR protein, which elevates HuR activity, and acts as a scaffold to interact with thioredoxin interacting protein (TXNIP) mRNA, increasing the stability of TXNIP mRNA, which then plays a protective role in lung adenocarcinoma." (PMID 37152286, 2023). "Compared to cisplatin-sensitive cells, cisplatin-resistant cells exhibit downregulation of TXNIP mRNA mediated by UCA1, suggesting a role of UCA1 and TXNIP in contributing to cisplatin resistance in lung adenocarcinoma." (PMID 37794178, 2023). "Overall, these results indicate that NCL overexpression can relieve the transcriptional suppression of TXNIP by MYC, leading to decreased activity and cytotoxicity of CD8+ T cells, ultimately promoting the growth, invasion, and survival of lung adenocarcinoma cells." (PMID 40346484, 2025). "These outcomes suggest that TXNIP overexpression can reverse the promoting effects of MYC on the infiltration ability of CD8+ T cells, thereby promoting the growth, invasion, and survival of lung adenocarcinoma cells." (PMID 40346484, 2025).
nonalcoholic fatty liver disease (12 papers, 2018 to 2025). "In a study, researchers investigated the possible role of TXNIP in type 1 diabetes-associated non-alcoholic fatty liver disease (NFALD) in the rat BRL-3A and human HepG2 cells." (PMID 33509217, 2021). "Overall, the SMS extract suppresses pyroptosis in non-alcoholic fatty liver disease through the TXNIP/NLRP3 pathway." (PMID 40926986, 2025). "For instance, Sal reduces drug-induced liver injury, guards the liver against ischemia/reperfusion injury, and eases nonalcoholic fatty liver disease (NAFLD) by AMPK-dependent TXNIP/NLRP3 pathway." (PMID 34054552, 2021). "In a previous study, it was reported that thioredoxin-interacting protein (TXNIP), an activator of NOD, LRR, and PYD domains-containing protein 3 (NLRP3) inflammasome, is associated with nonalcoholic fatty liver disease and T1DM." (PMID 32719778, 2020). "In a recent study, HFD-fed mice showed an increased expression of ChREBP and TXNIP, which is associated with HFD-induced nonalcoholic fatty liver disease (NAFLD)." (PMID 30733849, 2019). "Activation of thioredoxin-interacting protein (TXNIP)/nod-like receptor protein 3 (NLRP3) inflammasome plays a critical role in pathogenesis of non-alcoholic fatty liver disease." (PMID 30429827, 2018). "Additionally, verapamil can treat non‐alcoholic fatty liver disease by inhibiting the TXNIP/NLRP3 pathway and reducing the level of IL‐1β and IL‐18 to attenuate hepatic metaflammation." (PMID 34031983, 2021).
renal cell carcinoma (12 papers, 2020 to 2024). "TXNIP was revealed decreased expression in renal cell carcinoma, and its low expression was associated with advance tumor stages and poorer overall survival." (PMID 34484334, 2021). "CircRNA cRAPGEF5 can inhibit the metastasis of renal cell carcinoma via the miR-27a-3p/TXNIP pathway." (PMID 33262952, 2020). "On the other hand, a recent report showed that an increased level of TXNIP probably results from the activation of the JAK-STAT pathway and is associated with a favorable prognosis in patients with renal cell carcinoma." (PMID 32967107, 2020). "In the same context, renal cell carcinoma (RCC) tumors show high expression levels of UHRF1 compared to normal renal tissues, and this overexpression is associated with a decreased expression of the tumor suppressor gene TXNIP." (PMID 33922029, 2021). "Another study showed that Circ-RAPGEF5 was lowly expressed in renal cell carcinoma and exerted cancer-inhibiting effects in RCC via the miR-27a-3p/TXNIP pathway." (PMID 37705041, 2023). "The majority of these mutant genes have been reported to associate with tumorigenesis and metastasis of cancer cells, such as TXNIP in TNBCs and NSD1 in renal cell carcinoma." (PMID 35410320, 2022). "In renal cell carcinoma (RCC), UHRF1 recruits histone deacetylase 1 (HDAC1) into the TXNIP promoter, reducing TXNIP expression and promoting the progression of RCC." (PMID 35450411, 2022).
type 1 diabetes (12 papers, 2016 to 2025). "In vivo, type-1 diabetes modeled in rats caused increased TXNIP in peripheral blood along with decreased NO and VEGF, increased ROS, and increased inflammation-associated vascular cell adhesion molecule 1 (VCAM-1)." (PMID 33302545, 2020). "TXNIP deficiency in type 1 diabetes mice (Akita) efficiently decreased the blood glucose levels and finally increased mouse survival." (PMID 30168649, 2018). "TXNIP deficiency in mice significantly improved the features of a type 1 diabetes model." (PMID 30168649, 2018). "Finally, the findings of this study showed that targeting liver TXNIP by quercetin and allopurinol may be a therapeutic target in the prevention of type 1 diabetes-associated NAFLD." (PMID 33509217, 2021). "The role of TXNIP in inducing pancreatic cell death and causing type-1 diabetes appears to depend on properties not directly or exclusively related to its binding of TRX." (PMID 33302545, 2020). "TXNIP was also reported to implicate in the pathogenesis of type 1 diabetes and T2DM." (PMID 27731349, 2016). "Clinical trials confirm verapamil’s beneficial effects on β-cells via downregulation of TXNIP and IGFBP3 and upregulation of IGF-1 signaling in type 1 diabetes (T1D) patients." (PMID 40710367, 2025). "TXNIP DNA methylation and gene expression in subcutaneous adipose tissue, skeletal muscle and blood from offspring of women with gestational diabetes (O-GDM) or type 1 diabetes (O-T1DM) compared to offspring of women from the background population (O-BP) in univariate and multivariate analyses." (PMID 29077742, 2017).
colorectal cancer (11 papers, 2018 to 2025). A primary or metastatic malignant neoplasm that affects the colon or rectum. "This may be critical for HCC progression as downregulation of TXNIP and its impact on glucose metabolism has been recognized as a hallmark in prostate, lung, and colorectal cancer, and TXNIP downregulation was evident in HBV-related HCCs and contributed to cancer initiation." (PMID 36712976, 2022). "To assess the relative expression change of TXNIP after chemotherapy, compared to other transcripts, we used primary colorectal cancer cell lines (DLD1 and HCT15) and treated them with a clinically relevant concentration (10 μM) of oxaliplatin or vehicle." (PMID 39103698, 2024). "It has been established that TXNIP had a role in the development of colorectal cancer (CRC)." (PMID 39187523, 2024). "An increase in TRX and decrease in TXNIP expression might be the two sides of the same medal, which was demonstrated in cell lines, as well as in clinical samples of gastric and colorectal cancer patients." (PMID 33081035, 2020).
lactic acidosis (11 papers, 2010 to 2025). Metabolic acidosis characterized by the accumulation of lactate in the body. "Consistent with the function in regulating glucose uptake, a biallelic loss-of-function variant in TXNIP leads to lactic acidosis in three siblings." (PMID 41116060, 2025). "Loss of TXNIP causes specific metabolic alterations on the cellular level that are associated with neonatal lactic acidosis, recurrent hypoglycaemia, and specific anomalies in AA metabolism." (PMID 41116060, 2025). "Patients with decreased TXNIP levels due to Txnip gene mutations exhibit symptoms primarily characterized by lactic acidosis and low serum alanine levels." (PMID 38711073, 2024). "To define the role of TXNIP in the lactic acidosis gene expression, we compared the respective lactic acidosis response of the wild type and TXNIP deficient MEF cells by zero-transformation against the corresponding cells cultured in the control conditions." (PMID 20844768, 2010). "This induction of TXNIP under lactic acidosis is caused by the activation of the glucose-sensing helix-loop-helix transcriptional complex MondoA:Mlx, which is usually triggered upon glucose exposure." (PMID 20844768, 2010). "Although lactic acidosis causes stronger HIF1α protein expression compared to hydrochloric acidosis, it does not lead to increased glucose uptake due to the strong upregulation of TXNIP, a very potent suppressor of GLUT1 and a HIF1α destabilizing protein." (PMID 38195466, 2024). "In addition, the loss of TXNIP leads to many features of Warburg effects and glycolytic phenotypes of cancer cells, opposite to the influences of lactic acidosis." (PMID 20844768, 2010). "Importantly this induction of reporter activity under lactic acidosis was reduced by 61% with mutation in the ChoRE of the TXNIP promoter, indicating the importance of the ChoRE regions to the transcriptional activation of TXNIP under lactic acidosis." (PMID 20844768, 2010). "This analysis showed that the loss of TXNIP reduced the induction and repression of a significant number of genes as shown in the three gene clusters, including the repression of many cell-cycle related genes under lactic acidosis." (PMID 20844768, 2010). "For example, lactic acidosis triggers MondoA-dependent TXNIP expression and decreased glucose uptake." (PMID 30717828, 2019). "We previously showed that lactic acidosis drives MondoA localization to the TXNIP promoter, raising the possibility that lowering intracellular pH increases MondoA transcriptional activity." (PMID 30717828, 2019). "TXNIP expression is driven by a number of cellular stresses, including serum starvation, lactic acidosis/low pH, ultraviolet and gamma irradiation, endoplasmic-reticulum stress and microgravity." (PMID 30717828, 2019). "Conversely, some studies showed that increase in TXNIP expression is an important switch in response to stress conditions, such as oxidative stress, hypoxia and lactic acidosis, to induce trans-epithelial migration and metastasis of tumor cells." (PMID 30627326, 2018). "Previous studies have suggested that glutamine deprivation and lactic acidosis affect glucose metabolism through the induction of TXNIP by the transcription complex MondoA/Mlx." (PMID 25849282, 2015). "To further determine the role of MondoA in the induction of TXNIP under lactic acidosis, we used two different sets of siRNAs to knock down MondoA by gene silencing." (PMID 20844768, 2010). "Consistent with the previously known role of TXNIP to inhibit glucose uptake, the silencing of TXNIP by siRNAs led to significant decrease in the reduction of glucose uptake under lactic acidosis culture condition." (PMID 20844768, 2010). "Expression levels of TXNIP and ARRDC4 in human cancers are also highly correlated with predicted lactic acidosis pathway activities and associated with favorable clinical outcomes." (PMID 20844768, 2010).
lactic acidosis (continued). "Taken together, these results demonstrate the critical role of MondoA in regulating TXNIP under both glucose exposure and lactic acidosis." (PMID 20844768, 2010). "Taken together, these data showed that TXNIP induction contributes to the inhibition of glycolysis phenotypes, metabolic reprogramming, and cell cycle arrest and gene expression under lactic acidosis." (PMID 20844768, 2010). "In contrasts, lactic acidosis only reduced the glucose uptake by 28% in TXNIP knockout (TKO) MEF cells." (PMID 20844768, 2010). "The silencing of MondoA also led to increased glucose uptake under both control and lactic acidosis condition, a result similar to the silencing of TXNIP." (PMID 20844768, 2010). "Our findings identify lactic acidosis as a novel stimulus for the activation of MondoA and induction of TXNIP/ARRDC4." (PMID 20844768, 2010). "The three probe sets with the largest induction levels under lactic acidosis were all associated with thioredoxin interacting protein (TXNIP or Vitamin D3-upregulated protein 1, VDUP1)." (PMID 20844768, 2010). "When we examined expression of MCF-7 and HMEC under lactic acidosis at different time points, we also noted significant induction of TXNIP and its parralogue alpha-arrestin domain containing 4 (ARRDC4)." (PMID 20844768, 2010). "However, during lactic acidosis, the parallel upregulation of TXNIP counteracts this mechanism and glucose consumption is reduced to a larger extent compared to hydrochloric acidosis." (PMID 38195466, 2024). "Western blot analyses showed a strongly reduced c-MYC2 expression, particularly during lactic acidosis, which may explain increased TXNIP expression during lactic acidosis." (PMID 38195466, 2024). "Importantly, the expression of TXNIP and ARRDC4 are tightly associated with predicted lactic acidosis pathway activities and correlated with favorable clinical outcomes in human cancers." (PMID 34916487, 2021). "Thus lactic acidosis and glucose exposure are both potent inducers of TXNIP with synergistic induction potential, suggesting distinct mechanisms of TXNIP induction by these two stimuli." (PMID 20844768, 2010). "Glucose (4.5g/dL) or lactic acidosis alone increased TXNIP levels by approximately 4–5 fold." (PMID 20844768, 2010). "Although the TXNIP gene silencing reduced the glycolysis inhibition under lactic acidosis, the effects were modest, which may be due to the remaining level of TXNIP." (PMID 20844768, 2010). "Although gene silencing led to significant reduction of MondoA, the remaining MondoA level may still account for the slight induction of TXNIP under lactic acidosis." (PMID 20844768, 2010). "The lactic acidosis-induced cell cycle arrest may be caused by many changes, including the induction of AMPK, mTOR inhibition, TXNIP and cell cycle arrest caused by the induction p57, p21 and other inhibitors of cellular proliferation." (PMID 20844768, 2010). "Importantly, the re-introduction of full length MondoA back to the MEF cells fully restored the induction of TXNIP under lactic acidosis." (PMID 20844768, 2010). "Therefore, the upregulation of TXNIP under lactic acidosis make it an attractive candidate contributing to the anti-Warburg effects and inhibition of tumor glycolysis under lactic acidosis." (PMID 20844768, 2010). "We first tested the influence of lactic acidosis on the reporter constructs driven by the promoters of TXNIP and ARRDC4 and found that lactic acidosis could induce the reporter activities of both constructs by more than 6 folds." (PMID 20844768, 2010). "Therefore, the upregulation of TXNIP significantly contributes to inhibition of tumor glycolytic phenotypes under lactic acidosis." (PMID 20844768, 2010). "TXNIP was strongly induced by lactic acidosis, and suppressed by glucose deprivation." (PMID 20844768, 2010). "In addition, lactic acidosis also induced TXNIP expression in other cancer cell lines, including WiDr (colon cancer cell) and SiHa (cervical cancer cell)." (PMID 20844768, 2010).
lactic acidosis (continued). "In the presence of both high glucose levels and lactic acidosis, TXNIP was induced up to 18 fold." (PMID 20844768, 2010). "In addition, TXNIP is known for other properties, which may explain its effect on the gene expression during lactic acidosis." (PMID 20844768, 2010). "As a key paralogue of thioredoxin interacting protein (TXNIP), ARRDC4 involves in suppressing cancer glycolytic phenotypes under lactic acidosis." (PMID 34916487, 2021). "For example, genes such as TXNIP and ARRDC4, which are both indicative of lactic acidosis, correlate with better clinical outcomes, and contribute to predicting tumors with intact NF1 signaling." (PMID 28166733, 2017). "We detected increased specific binding of MondoA to the promoter regions of TXNIP and ARRDC4 with more acidic lactic acidosis environments." (PMID 20844768, 2010). "MondoA is likely to be more relevant in the observed lactic acidosis response of MCF-7 given its higher expression levels in MCF-7 and the simultaneous upregulation of both TXNIP and ARRDC4 under lactic acidosis." (PMID 20844768, 2010). "Among these selected genes, TXNIP and its paralogue ARRDC4 are both induced under lactic acidosis and repressed with glucose deprivation." (PMID 20844768, 2010). "This difference may result from the upregulation of TXNIP, an inhibitor of GLUT1-expression and glycolysis, which is more upregulated under lactic acidosis than in hydrochloric acidosis." (PMID 38195466, 2024). "This suppression of glucose uptake requires both MondoA and TXNIP, yet the mechanisms by which lactic acidosis activates MondoA transcriptional activity was not investigated." (PMID 30717828, 2019). "In addition, we found the silencing of TXNIP in MCF-7 increased both the glucose consumption and lactate productions under normal media, but lactic acidosis significantly reduced both the glucose consumption and lactate production in all treated cells." (PMID 20844768, 2010). "During lactic acidosis, the level of MondoA protein did not change, while TXNIP was induced significantly." (PMID 20844768, 2010). "In the complete absence of MondoA, both the basal and inducible level of TXNIP under 2-DG or lactic acidosis was completed abolished." (PMID 20844768, 2010). "We also tested the ability of lactic acidosis to repress the proliferation of MEF cells and found that the proliferation of the wild type, but not TXNIP deficient MEF cells, were repressed by lactic acidosis." (PMID 20844768, 2010). "Therefore, the expression of both TXNIP and ARRDC4 are potentially important mediators of the lactic acidosis response and suggest the important prognostic significance of molecular pathways driven by Mondo-Mlx in human cancers." (PMID 20844768, 2010). "The strong upregulation of TXNIP and its paralogs ARRD2 and ARRD4 by chronic acidosis is consistent with previous reports of the effect of acidosis and lactic acidosis on this family of proteins, which are key negative regulators of glycolytic metabolism." (PMID 32764426, 2020).